ZNF875 (zinc finger protein 875)
Description:
May be involved in transcriptional regulation.
Synonyms: HKR1
Tractability: PROTAC: ubiquitination databases record sites on it.
Gene: Protein-coding gene on chromosome 19 (37,312,837 to 37,369,365, forward strand). Ensembl gene ENSG00000181666.
Subcellular location: Nucleus
Subcellular location (Human Protein Atlas): Mitochondria; Nucleoplasm
Pathways (Reactome):
Gene expression (Transcription): Generic Transcription Pathway
Gene Ontology:
Molecular function: DNA-binding transcription factor activity, RNA polymerase II-specific; RNA polymerase II transcription regulatory region sequence-specific DNA binding; sequence-specific DNA binding; zinc ion binding
Biological process: regulation of transcription by RNA polymerase II; regulation of DNA-templated transcription
Cellular component: nucleus
Genetic constraint (gnomAD): Loss-of-function variants: 10 observed, 7.64 expected, observed/expected ratio (o/e) 1.31, 90% interval 0.79 to 1.88. That is too few expected variants to judge how well the gene tolerates losing a copy. Missense variants: 709 observed, 756.44 expected, observed/expected ratio (o/e) 0.94, 90% interval 0.88 to 1. Synonymous variants: 281 observed, 280.28 expected, observed/expected ratio (o/e) 1, 90% interval 0.91 to 1.11.
Homologues: Orthologues: chimpanzee ZNF875 (97% identical), macaque ZNF875 (95% identical), dog ZNF875 (83% identical), Drosophila melanogaster Phs (20% identical), Drosophila melanogaster CG3281 (20% identical), Drosophila melanogaster CG2712 (19% identical). Paralogues in human: ZNF133 (55% identical), ZNF169 (49% identical), ZNF337 (47% identical), ZNF343 (46% identical), PRDM9 (42% identical), ZNF805 (34% identical), ZNF264 (34% identical), ZNF614 (33% identical), ZNF25 (33% identical), ZNF425 (33% identical), ZFP90 (33% identical), ZFP37 (32% identical), and 50 more.
Diseases named in the same sentence as ZNF875 in open-access papers:
ZNF875 is named in the same sentence as 5 diseases in open-access papers, as found by Europe PMC text mining. Sharing a sentence is not in itself a finding about the gene and the disease. The quoted sentences say what the papers report.
lung carcinoma (4 papers, 2018 to 2024). "In addition, a factor with high homology to ZNF133, HKR1 (also known as ZNF875), exhibited increased expression in lung cancer, which was even more pronounced upon the treatment with platinum drugs." (PMID 33672287, 2021).
ZNF875 also shares sentences with these, for which no sentence is quoted: adenocarcinoma (1 paper); Alzheimer disease (1); colorectal carcinoma (1); tumor (1).